HOXC11 (homeobox C11)
Diseases named in the same sentence as HOXC11 in open-access papers (continued):
Sharing a sentence is not in itself a finding about the gene and the disease.
neuroblastoma (1 paper, 2019). Neuroblastoma (NB) is the most common solid, extracranial childhood tumor. "HOXC6 and HOXC11 have been shown to induce differentiation of GOTO neuroblastoma cells into Schwannian cells via transcription activation of S100β." (PMID 31379707, 2019).
T-cell acute lymphoblastic leukemia (1 paper, 2014). Acute lymphoblastic leukemia of T-cell origin. "HOXC11 protein was localized earlier in the nucleus of T-cell acute lymphoblastic leukemia." (PMID 25080327, 2014).
cancer (16 papers, 2015 to 2025). A tumor composed of atypical neoplastic, often pleomorphic cells that invade other tissues. "Activation of HOXC9 and HOXC11 in various cancers has been associated with cell proliferation and invasion." (PMID 28402266, 2017). "Intriguingly, we observed that the intron region of SNP rs4759314 resided performed a promoter activity from ENCODE data, and gene HOXC11 was only located in about 5-kb downstream of SNP rs4759314, which was involved in the development and outcome of cancer." (PMID 26384301, 2015). "High expression of genes such as HOXB5, HOXC11, HOXA13, HOXD13, HOXA6, and HOXC6 in certain cancers is linked to poor overall survival (OS)." (PMID 39980564, 2025). "In our study, a high level of IKKα facilitated the progression of LUAD by stabilizing HOXC11 from degradation via the ubiquitin-proteasome pathway and upregulating the protein level of HOXC11, suggesting a potential cancer-promoting role for IKKα." (PMID 36823149, 2023). "HOTAIR, which is likewise found on chromosome 12q13.13 and is an oncogenic lncRNA in a variety of cancers, is an antisense transcript of HOXC11." (PMID 36031658, 2022). "For example, as a well-known lncRNA, HOTAIR, also located at chromosome 12q13.13, is an antisense transcript of HOXC11 and was an oncogenic lncRNA in many different types of cancer." (PMID 30286788, 2018). "Our analysis of expression data obtained from a cohort of cancer samples revealed a strong positive correlation between Hotair and Hoxc11 expression, also observed in our mouse wild type samples." (PMID 27977683, 2016). "Moreover, overexpressing HOXC11 was found to promote cancer cell proliferation and migration." (PMID 35155451, 2021). "Therefore, while Hotair may indeed be involved in a variety of cancer conditions, it is likely that its over-expression in cancer cells is accompanied by Hoxc11 over-expression, which may again confound the observed phenotypes." (PMID 27977683, 2016). "Genes involved in angiogenesis (HOXA2, HOXC5), genome instability (HOXC5, HOXC11), deregulating cellular energetics (HOXA4, HOXC5), and metastasis (HOXA2) were all up-regulated in ecDNA(+) cancers." (PMID 38896472, 2024). "HOTAIR has been observed to be involved in the regulation of cancer cell proliferation and cancer invasion in breast cancer which could arise from the positive correlation between HOTAIR and Hoxc11 genes." (PMID 29732012, 2018). "Of the genes that were altered in all cancer subtypes, the expression of five matched all datasets (HOXC8, HOXC11, HOXD8, PROX1, SIX2), although the overlap was found when considering the expression in the majority of the subtypes as HOXC11 and PROX1 were downregulated in TN CSC." (PMID 28202042, 2017).
tumor (16 papers, 2011 to 2025). "IHC staining of RCC tissues indicated a strong correlation between HOXC11 and Ki67 expression, indicating that HOXC11 promotes tumor proliferation and, therefore, a worse prognosis." (PMID 39858044, 2025). "Silencing HOXC11 expression significantly reduced tumor cell proliferation and impaired colony-forming capacity, confirming that HOXC11 promotes the proliferative phenotype of ACC cells." (PMID 41037214, 2025). "Using a random forest algorithm, we identified HOXC11 as a key prognostic factor within MACCS1, with high expression associated with tumor progression." (PMID 41037214, 2025). "Constructing subcutaneous xenograft tumor models and comparing the tumor formative ability found that HOXC11 knockout impaired the ability of tumor formation of PC9 cells." (PMID 36823149, 2023). "In the tumour tissue and in primary cell cultures derived from patient tumours, both HOXC11 and SRC-1 translocate to the nucleus with a high level of coassociation." (PMID 21654685, 2011). "Moreover, HOXC11 expression was markedly elevated in ACC tumor tissues compared with adjacent normal tissues, and was significantly higher in advanced-stage tumors (T3/T4) than in early-stage tumors (T1/T2), implicating its role in disease progression." (PMID 41037214, 2025). "Due to the tumor-promoted mechanisms of HOXC11 remains unclear, we used GSEA to enrich some HOXC11 expression-related genes, including CCL5, HBA2, and SPHK1, and then detected their mRNA expressive levels in HOXC11 overexpressed cells." (PMID 36823149, 2023). "Furthermore, reverting HOXC11 expression in HOXC11 knockout cells reversed this trend, demonstrating that the HOXC11 protein can promote tumor development in LUAD." (PMID 36823149, 2023). "HOXC11 expression was well correlated with HOTAIR expression in tumor tissues (r Pearson = 0.96)." (PMID 25994132, 2015). "Similar incident happened in case of HOXC11 too, where downregulation of this gene is known to suppress tumour formation and hence the phenomenon could be considered as body’s balancing act to check the tumour growth." (PMID 31795960, 2019). "Functionally, HOXC11 knockdown significantly reduced proliferation and colony formation in vitro, confirming its role in ACC tumor growth." (PMID 41037214, 2025). "Three were canonical oncogene drivers, namely HOXC11, SOX2, and KCNJ5, while the rest 25 are putative oncogenes and putative tumor suppressors in almost equal measure." (PMID 39484215, 2024). "Among them, HOXC11, HOXC10, HOXC8, and HOXC12 interact with HOTAIR in gastrointestinal tumors to jointly promote tumor formation and development." (PMID 36924407, 2023). "On the contrary, the ability of proliferation, migration, invasion, colony formation, and subcutaneous xenograft tumor formation in LUAD cells was significantly decreased, and the cell cycle slowed down after HOXC11 knockout." (PMID 36823149, 2023). "Dasatinib-treated mice maintained ERα status and reduced primary tumor expression of p-Src kinase, the co-activator SRC-1, the transcription factor HOXC11, and their target gene S100β." (PMID 28399921, 2017). "For the posterior HOXC genes we observed a significant reactivation of HOXC11 and HOXC13 in tumor tissues (HOXC13 p = 0.001)." (PMID 25994132, 2015). "This study supports the hypothesis that expression of HOXC11 and the subsequent secretion of PSAP can expedite endocrine resistance to aromatase inhibitor therapy via tumour promotional activation of the AR." (PMID 26341737, 2015). "In that study, HOXC11 overexpression rescued ART-induced effects on proliferation, migration, apoptosis, and ferroptosis by activating PROM2/PI3K/AKT signaling, whereas PROM2 silencing restored sensitivity to ART and tumor suppression both in vitro and in vivo." (PMID 40826138, 2025).
tumor (continued). "The results revealed that the expression level of PCOLCE2 and HOXC11 in COAD patients was significantly higher than that in healthy individuals, regardless of for M tumor stage, lymph node metastasis and peritoneal metastasis (p < 0.05)." (PMID 35155451, 2021).
infection (1 paper, 2012). The state of being infected such as from the introduction of a foreign agent such as serum, vaccine, antigenic substance or organism. "Paradoxically, we observed that total H3K27me3 levels increase over time in infected fibroblasts, and our ChIP data revealed a significant increase in H3K27me3 enrichment at the HoxC11 promoter over the course of infection." (PMID 22279536, 2012). "Over the course of infection, we also noticed a significant increase in H2K27me3 at the HoxC11 promoter by 6 hpi, suggesting infection may impact cellular targets of PRC2." (PMID 22279536, 2012).
HOXC11 also shares sentences with these, for which no sentence is quoted: cutaneous melanoma (2 papers); lung adenocarcinoma (2); Fanconi anemia (1); gastrointestinal tumors (1); hemangioblastoma (1); hepatocellular carcinoma (1); keloid (1); leukemia (1); metastatic melanoma (1); nasopharyngeal carcinoma (1); oral cancer (1); ovarian carcinoma (1); renal carcinoma (1); renal cell carcinoma (1); renal clear cell carcinoma (1); renal fibrosis (1); retinoblastoma (1); stomach carcinoma (1).